PIN1 (peptidylprolyl cis/trans isomerase, NIMA-interacting 1)
Diseases named in the same sentence as PIN1 in open-access papers (continued):
Sharing a sentence is not in itself a finding about the gene and the disease.
cancer (continued). "Compound 8 efficiently inhibited PIN1 (IC50 = 0.43 μM) and it was able to affect the proliferation of breast MDA-MB-231 cancer cells in which PIN1 is overexpressed, also reducing the viability of induced cancer stem cell-like cells." (PMID 30723410, 2018). "Taken together, these results demonstrate that Pin1 is highly overexpressed in human AML and is a promising therapeutic target to block multiple cancer pathways in AML." (PMID 29848341, 2018). "Several PIN1 inhibitors including ATRA and KPT-6566 have been shown to inhibit cancer cells proliferation in vitro and in vivo." (PMID 30534074, 2018). "Pin1 not only suppresses the DAN damage-induced senescence and apoptosis but also contributes the genome instability in cancers." (PMID 30158600, 2018). "In summary, our results not only reveal a novel anticancer mechanism for ATO, but also provide the first evidence that ATO, particularly in combination with ATRA, blocks multiple cancer-driving pathways and eliminates TICs in TNBC by targeting Pin1." (PMID 30093655, 2018). "Pin1 is prevalently overexpressed in human cancers including ~70% of HCC, and promotes tumorigenesis by activating multiple cancer-driving pathways." (PMID 28262728, 2017). "As a global regulator of phosphor-proteins with Ser/Thr-Pro motif, Pin1 regulates multiple cancer-driving pathways in various HCC cell lines, making Pin1 as an ideal target for treating this heterogeneous cancer." (PMID 28262728, 2017). "In other cancer cell lines HepG2 and A549, ATF1 transcriptional activation of Bcl-2 was also impaired by knockdown of Pin1." (PMID 28032861, 2016). "Little is known about PPIC in cancer, however PPIA and another PPIase PIN1 have been shown to interact with key growth and signalling proteins including cyclin D1, CDK10, cdc27, and PLK1, with diverse downstream effects on MAPK signalling." (PMID 27852308, 2016). "Consistent with these tumor-promoting functions, aberrant expression of several key molecules of the KLHL20/PML pathway, such as HIF-1α, Pin1, and PML, has been reported in many types of cancers." (PMID 27042198, 2016). "In addition to promoting cell death, DAPK elicits other anti-cancer functions, such as suppression of metastasis by regulating cell migration, adhesion, and cytoskeleton remodeling and inhibition of cell transformation by inactivating the phospho-Ser/Thr directed isomerase Pin1." (PMID 27042198, 2016). "Such inhibitors would also be highly valuable molecular probes for further investigation of PIN1 regulation of NRF2 in the cellular context, and potentially pave the way for drug molecules that specifically inhibit the cytoprotective effects of NRF2 in cancer." (PMID 40087364, 2025). "There is no doubt that combination therapies targeting Pin1-related cancer signaling pathways or the creation of novel Pin1-specific inhibitors, will open up new treatment options for both the prevention and management of cancers." (PMID 41246306, 2025). "PIN1P1 is the pseudogene of the critical oncogene PIN1, but has not yet been investigated in human cancer." (PMID 37929660, 2024). "Therefore, when Pin1 is overexpressed and CDK is constitutively expressed, like in cancer cells, the G1/S regulatory checkpoint breaks down as the APC/CCDH1 is inhibited and the cell proliferates unchecked." (PMID 38727267, 2024). "Thus, APC/CCDH1 is likely the physiological E3 ubiquitin ligase for PIN1, and its activity is primarily inhibited by phosphorylation of CDH1 in cancer cells." (PMID 38622115, 2024). "Despite the in-vivo validation of the anti-cancer effects of juglone, its lack of specificity to Pin1 and the nature and diversity of its numerous off-target interactors limit the use of juglone as a potential cancer therapeutic." (PMID 38745861, 2024).
cancer (continued). "Moreover, on binding to the catalytic site of Pin1, a quinone-mimicking drug from KPT-6566, induces apoptosis in multiple types of cancers." (PMID 39624096, 2024). "Studies have demonstrated that, unlike in malignant tumors, Pin1 is poorly expressed in neurological disorders." (PMID 38891776, 2024). "In cancer, PIN1 is frequently overexpressed and APCCDH1 frequently inactivated through phosphorylation, creating a wide therapeutic window for combined inhibition of CDK4 and PIN1." (PMID 38622115, 2024). "Last but not least, all the regulatory enzymes discovered in this study, including USP34, Pin1, Plk1, CDK1 and Ubc9, could be effective drug targets for combination therapies to treat GBMs and potentially other malignant tumors." (PMID 38167292, 2024). "The expression of PIN1 was significantly increased in cancer tissues and HEp-2 cells, and there was a targeted relationship and negative correlation between miR-150-5p and PIN1 in cancer tissue." (PMID 37105032, 2023). "We also compared Pin1 expression between NCCIT cells and multiple human cancer cell lines." (PMID 38020885, 2023). "Western blotting showed that Pin1 expression was up-regulated in the cancer cell lines compared to the non-tumorous counterpart, which displayed low basal expression of Pin1 protein." (PMID 37050909, 2023). "Furthermore, Pin1 binds to the pSer929-Pro site in HIP1R, which in turn promotes actin binding and ultimately drives PD-L1 on cancer cells into lysosomal degradation." (PMID 36759842, 2023). "It is possible that PIN1 might be directly or indirectly involved in the tumor suppressor function of RUNX3, and the regulation could be cell-type- or cancer-type-specific." (PMID 36899853, 2023). "Multiple studies have identified that Pin1 contributes to the progression of diverse human cancers, but its role in TGCT had not previously been determined." (PMID 38020885, 2023). "The peptidylprolyl cis–trans isomerase NIMA-interacting 1 (Pin1) has been considered to be a novel biomarker for the stratification of TNBC patients for treatment, in order to improve the management of poor outcome of cancer." (PMID 35450041, 2022). "Additionally, Pin1 promotes invasion and metastasis through activation of p53M and BRD4 in many cancers." (PMID 33807199, 2021). "Additionally, Pin1 upregulates TGF-β through stabilizing its mRNA, which acts a crucial regulator of immune responses, leading to immune escape for cancer development." (PMID 33807199, 2021). "We observed a significantly different rate of non-progression between cancer patients with Pin1-negative and Pin1-positive statuses, and this is the first study to demonstrate a role for Pin1 IHC as a triage tool for LSIL biopsies." (PMID 32010480, 2020). "Pin1 also interacts with Fbw7 and CDK10 in a phosphorylation-dependent manner and promotes their ubiquitination and degradation, which suppresses their function to trigger cell proliferation and transformation of cancer cells." (PMID 32296699, 2020). "In addition to temporally regulating MYC activity, PIN1 regulates the subnuclear localization of MYC under normal mitogen stimulation conditions, during wound healing, and in cancer cell lines." (PMID 32300594, 2020). "For two other types of cancer the relationship of survival profile with Pin1 expression is non-determined." (PMID 32426354, 2020). "Pin1 also enhances BRCA1-BARD1 interaction with RAD51, thereby increasing the presence of RAD51 at stalled replication structures and governing replication fork protection during cancer development." (PMID 32296699, 2020). "KPT-6566 is able to specifically inhibit the vitality of Pin1-overexpressing cancer cells while not affecting normal cells." (PMID 32010480, 2020). "The current understanding stems primarily from observations that Pin1 is overexpressed/has increased activity in most cancers and cancer stem cells, with corresponding negative prognostic outcomes." (PMID 32426354, 2020).
cancer (continued). "Indeed, PIN1 is transcriptionally regulated by E2F in response to growth factors and by NOTCH1/4 activation in cancer." (PMID 30873382, 2019). "ATRA exhibited very limited inhibitory effects on cell viability of these epithelial cells, likely because ATRA selectively targets active Pin1 in cancer cells, but not in normal cells with low Pin1 levels." (PMID 31867329, 2019). "Hence the detailed understanding about how Pin1-YAP/TAZ regulates each other will provide a novel strategy for the successful treatment of drug resistance and tumorigenecity of cancers." (PMID 31015482, 2019). "Tau, Pin1 and PARN target the expression of mRNAs deregulated in AD and/or cancer." (PMID 31749682, 2019). "We found that PIN1 and PTOV1 both hold promising target to change the redox status of cancer cells." (PMID 31083670, 2019). "Our study provides evidence that inhibition of Pin1 decreases the Taxol resistance induced by YAP/TAZ overexpression in MCF10A mammary cells, indicating that Pin1 co-operates with YAP/TAZ to induce drug resistance in many cancer cells." (PMID 31015482, 2019). "Thus, synergistic targeting of Pin1 by ATO and ATRA offers an attractive approach to combating breast and other cancers." (PMID 30093655, 2018). "Moreover, 11 impaired PIN1-dependent invasive behavior of breast (MDA-MB-231) and prostate (PC3) cancer cells." (PMID 30723410, 2018). "Further studies are required to identify specific and non-toxic PIN1 inhibitors for the treatment of cancers with PIN1 over-expression." (PMID 30534074, 2018). "Overexpression of both PIN1 and HIF-1α is prevalent in many types of human cancer." (PMID 26784107, 2016). "Protein interacting with NIMA (never in mitosis A)-1 (Pin1) is overexpressed in several human cancers and correlated with poor outcome of patients." (PMID 25160749, 2014). "Altogether, such inhibitors would also be highly valuable molecular probes for further investigation of PIN1 regulation of NRF2 in the cellular context and potentially pave the way for drug molecules that specifically inhibit the cytoprotective effects of NRF2 in cancer." (PMID 40087364, 2025). "MRC-5 cells were chosen as the optimal model for PF studies due to their significantly higher Pin1 expression compared to AEII cells, alongside their normal lung fibroblast characteristics, which better represent fibrotic conditions compared to epithelial cancer cell lines." (PMID 41477119, 2025). "However, in spite of high PIN1 expression in cancer cells, L1 expression is also upregulated, indicating dysregulation of other L1 regulatory mechanisms independent of PIN1 or reduced PIN1 nuclear activity in the presence of L1 ORF1." (PMID 36707636, 2023). "Pin1 enhances cell proliferation by induction of cyclinD1 and regulates the expression of numerous mitosis-specific phosphoproteins whose levels change during the cell cycle in normal cells but not in cancer cells." (PMID 37754262, 2023). "Developing chemical agents that inhibit Pin1 rather than Hap90 ATPase activity could be a promising approach for cancer chemotherapy." (PMID 36829834, 2023). "However, when TNBC cells are treated with ATO and ATRA, ATRA induces AQP9 and increases the uptake of ATO by cancer cells, while at the same time ATRA cooperatively inhibits Pin1 as well as other oncogenic pathways, such as NF-κB, β-catenin, c-Myc, Akt, and c-Jun." (PMID 38136293, 2023). "PIN1 could also bind a variety of metabolic regulators including AMP-activated protein kinase, acetyl CoA carboxylase and pyruvate kinase 2 and regulate lipid/glucose metabolism in cancer cells, thereby to promote tumor progression." (PMID 36813923, 2023). "Pin1 drives pro-connective tissue proliferation and immunosuppressive TME and promotes tumor malignancy and drug resistance by acting on stromal cells such as CAF and by acting on pS929-HIP1R to induce endocytosis and degradation of PD-L1 and ENT1 in cancer cells." (PMID 36770689, 2023).
cancer (continued). "Furthermore, Pin1 also inhibits Rb- and PML-induced senescence in cancer cells." (PMID 33807199, 2021). "In addition, FOXM1B/C have been demonstrated to promote cancer progression through the interaction with other proteins, such as β‐catenin, STAT3, SMAD3, HSP70, nucleophosmin (NPM), maternal embryonic leucine‐zipper kinase (MELK), and Pin1." (PMID 33314660, 2021). "Downregulation of miRNA in cancer has a significantly negative correlation with Pin1 expression." (PMID 34722255, 2021). "Presently, several Pin1 inhibitors have been developed, such as miR-200b, miR-200c, and miR296-5p, the small molecules all-trans retinoic acid (ATRA) and KPT-6566, and the natural compound Juglone, which all showed anti-cancer activity in different types of cancer." (PMID 32630675, 2020). "Moreover, Pin1 cooperates with KLHL20 to induce the ubiquitin-dependent degradation of PML, an inhibitor of HIF-1α-induced angiogenesis, resulting in the activation of angiogenesis in many cancers." (PMID 32296699, 2020). "Given the critical role of Pin1 in maintaining the balance between cis- and trans-ATR in the cytoplasm, manipulation of Pin1 subcellular level or activity could be another means to control cis-ATR formation for cancer therapeutics." (PMID 32426354, 2020). "Moreover, Pin1 is also not applied in clinical cancer diagnosis, even though Pin1 seems to be a potential cancer-specific biomarker." (PMID 32296699, 2020). "A growing body of evidence highlighted that PIN1 can globally affect cellular plasticity and reprogramming by acting upstream and downstream to regulators of epithelial-to-mesenchymal transition (EMT), an embryonic process that is hijacked during cancer progression." (PMID 30873382, 2019). "In addition, several PIN1-targeting miRNAs that show a negative correlation with PIN1 expression have also been identified in other cancers." (PMID 30534074, 2018). "The dissociation constant of EGCG and Pin1 has been calculated as 21 μM, both by protease-coupled and isothermal titration calorimetric assays: this value is similar to the concentration of EGCG that was found to exert anti-cancer effects in experimental cancer models." (PMID 30563268, 2018). "Thus, targeting Pin1 represents a novel non-toxic strategy to simultaneously block multiple cancer-driving pathways and also eliminate TICs7,25." (PMID 30093655, 2018). "In this manuscript, we report the surprising findings that ATO inhibits and induces Pin1 degradation and suppresses cancer cell growth via noncovalently binding to the Pin1 active site, as corraborated by nuclear magnetic resonance (NMR) and co-crystal structure." (PMID 30093655, 2018). "Thus, targeting Pin1 represents a novel anticancer strategy to block multiple cancer pathways simultaneously without general toxic effects on normal tissues." (PMID 28262728, 2017). "Interestingly, we identified K117 residue as the poly-ubiquitination site of Pin1, but we did not detect the mono-ubiquitination of Pin1 in GSCs, suggesting that ubiquitin-proteasomal degradation of Pin1 proteins may differ in different cancers." (PMID 38167292, 2024). "Collectively, our study demonstrates the novel mechanism of PIN1/CDK1 to cooperatively destabilize pVHL and promote tumor progression, thereby targeting PIN1 and CDK1 might be potential therapeutic strategies in the treatment of TNBC and other cancers with wild-type VHL." (PMID 36813923, 2023). "Additionally, Pin1 expression seems to be correlated with cell proliferative capacity: very low expression of Pin1 is observed in non-proliferating cells, while its overexpression is observed in most human cancers including the colon, breast, lung, and also brain." (PMID 34523079, 2021). "However, to date, no Pin1 inhibitors are submitted to clinical trial for cancer treatment." (PMID 32296699, 2020).
cancer (continued). "Nonetheless, the use of liposomal formulations to vehicle a potent, but not cell-permeable, PIN1 inhibitor in cancer cells has shown effectiveness in curbing tumor growth in vivo, implying that such a strategy could be applied to other inhibitors with scarce pharmacokinetic properties." (PMID 30873382, 2019). "From these previous reports, Pin1 may also play a role for PKM2 translocation to the nucleus in OSCC, and cell cycle progression by cyclin D1 expression through nuclear PKM2 and β-catenin binding may also be one of the mechanisms of cancer cell progression in OSCC progression." (PMID 30333907, 2018). "Thus, Pin1 is a novel drug target for ATO, and synergistic targeting of Pin1 by ATO and ATRA offers an attractive approach to block multiple cancer-driving pathways and eliminate TICs, which are the two major sources of drug resistance in current cancer therapy." (PMID 30093655, 2018). "We found that binding of PIN1 with the c-terminal thr-pro motifs of NONO leads to increased stability and abundance of NONO, which in turn promotes tumorigenesis by activating cancer-promoting genes and inactivating tumor suppressors." (PMID 37370134, 2023). "PIN1 induces the interaction of non-receptor type 12 (PTP-PEST) with FAK to increase the FAK Tyr397 dephosphorylation, which induces cancer metastasis." (PMID 32258027, 2020). "However, the expression and function of PIN1P1 in human diseases, including cancers, and the effect of PIN1P1 on its parental gene PIN1 have not yet been documented." (PMID 37929660, 2024). "The results of our epistasis analysis do not seem to support a role for Pin1/PINN-1 as an obligatory step downstream of DAPK/DAPK-1, as might be inferred from mammalian cancer studies." (PMID 25899010, 2015). "Thus, cooperative Pin1 inhibition by ATO and ATRA potently blocks numerous oncogenic pathways and eliminates TICs, offering a promising non-toxic approach to fighting TNBC and likely many other cancers." (PMID 30093655, 2018).